MAF1 (MAF1 negative regulator of RNA polymerase III)
Diseases named in the same sentence as MAF1 in open-access papers (continued):
Sharing a sentence is not in itself a finding about the gene and the disease.
infection (6 papers, 2014 to 2022). The state of being infected such as from the introduction of a foreign agent such as serum, vaccine, antigenic substance or organism. "Here we identify mitochondrial association factor 1 (MAF1) as the parasite protein that mediates the association between the protozoan pathogen Toxoplasma and host mitochondria during infection." (PMID 24781109, 2014). "However, possibly at contrast with these ideas, it was demonstrated that MHV68 infection induced tRNA upregulation in wild-type and Maf1-deficient cells." (PMID 35458509, 2022). "In Δgra45 parasites, PVM localization of MAF1 was completely abolished at the early infection stage (4 h p.i.) and significantly reduced at 24 h p.i.." (PMID 33067458, 2020). "Using Gene Set Enrichment Analysis (GSEA), we found that canonical immune pathways, including JAK-STAT, NFAT, and IL10, were among the most significantly enriched gene sets up-regulated during type II:MAF1 infection relative to type II wild type." (PMID 24781109, 2014). "In support of this, there is considerable overlap between tRNA genes upregulated during MHV68 infection with those upregulated in cells lacking Maf1, a negative regulator of RNAPIII that prevents polymerase recruitment." (PMID 33323507, 2020). "Although our results confirm that MAF1 is not a major virulence determinant using the crude measure of mortality by intraperitoneal infection in mice, they did not address the possibility of other differences in the host response to infection by type I and type I:Δmaf1 parasites." (PMID 24781109, 2014).
brain diseases (1 paper, 2020). "Our findings highlight novel of Maf1 in regulating NLRP3 activation and also suggest a potential therapeutic role for Maf1 in treating brain diseases associated with BBB disruption." (PMID 33424842, 2020).
neurodegenerative disease (1 paper, 2020). A disorder of the central nervous system characterized by gradual and progressive loss of neural tissue and neurologic function. "Regulation of Maf1 might be a therapeutic strategy for SAE and other neurodegenerative diseases associated with inflammation." (PMID 33424842, 2020).
MAF1 also shares sentences with these, for which no sentence is quoted: Cognitive impairment (2 papers); Encephalopathy (2); nonalcoholic fatty liver disease (2); anthrax (1); cerebral small vessel disease (1); cholangiocarcinoma (1); coloboma (1); COVID-19 (1); diabetes mellitus (1); edema (1); fatty liver disease (1); heart failure (1); hypertrophy (1); metabolic disease (1); metastatic tumors (1); Optic neuropathy (1); osteosarcoma (1); plague (1); Septicaemia (1); triple-negative breast carcinoma (1); viral infection (1).